HSF1 (heat shock transcription factor 1)
Diseases named in the same sentence as HSF1 in open-access papers (continued):
Sharing a sentence is not in itself a finding about the gene and the disease.
pancreatic cancer (continued). "Our study showed that downregulation of HSF1 promotes both SMAC expression and apoptosis in pancreatic cancer cells." (PMID 28482903, 2017). "Thus, our findings suggest that HSF1 may be an independent predictor of survival and prognosis in patients with pancreatic cancer and may serve as a target for the diagnosis and treatment of pancreatic cancer." (PMID 28482903, 2017). "Regarding the molecular mechanism, HSF1 downregulates SMAC expression to inhibit mitochondrial apoptosis in pancreatic cancer cells, thus promoting pancreatic cancer." (PMID 28482903, 2017). "We selected four pancreatic cancer cell lines (ASPC-1, BXPC-3, CFPAC-1 and PANC-1) and verified differences in HSF1 expression by Western blot and RT-PCR analyses." (PMID 28482903, 2017). "Our study indicates that like pancreatic cancer, triptolide inhibits Sp1 in gastric cancer as well to downregulate HSP70 and HSF1 to induce cell death." (PMID 28192510, 2017). "Based on our previous finding that the loss of AMPK activation was a frequent event in pancreatic cancer, in the present study, we hypothesized that AMPK inactivation promotes the amplification and abnormal activation of the tumor‐promoting HSF1, thus promoting pancreatic cancer progression." (PMID 28783244, 2017). "The in vivo and in vitro activation of AMPK impaired the activity of HSF1, and HSF1 mediated the effects of the AMPK knockdown‐induced pancreatic cancer invasion and migration." (PMID 28783244, 2017). "First, immunohistochemical staining was performed to detect the expression of p‐HSF1 and p‐AMPK in different stages of pancreatic cancer." (PMID 28783244, 2017). "The knockdown of HSF1 impaired the invasion and migration and epithelial–mesenchymal transition (EMT) of pancreatic cancer cells in vitro; however, the upregulation of HSF1 showed the opposite effects." (PMID 28783244, 2017). "After observing the antagonistic relationship between BAP1 and SIRT1, particularly in their convergence on the K80 acetylation of HSF1, we became intrigued by the potential efficacy of combining SIRT1 inhibition with ICB therapy in models of pancreatic cancer characterized by BAP1 deletion." (PMID 39350280, 2024). "For the in vitro assay, we plated acinar cell clusters from KC/C mice in 3D conditions and treated them with KRIBB11 or not to explore the role of HSF1 on the initiation of pancreatic cancer in vitro." (PMID 33422093, 2021). "Additionally, HSF1 was found to be required for EMT in ovarian cancer (including a spheroid growth model), hepatocellular carcinoma, and pancreatic cancer." (PMID 32268506, 2020). "Furthermore, our study confirms that HSF1 induces the expression of HSPs and regulates the SMAC-mediated mitochondrial apoptosis pathway to inhibit pancreatic cancer cell apoptosis and promote tumorigenesis." (PMID 28482903, 2017). "Therefore, we propose a new molecular model in which HSF1 regulates SMAC-mediated mitochondrial apoptosis by modulating the expression of HSPs, leading to tumorigenesis and development of pancreatic cancer." (PMID 28482903, 2017). "Besides, the pharmacological inhibition of HSF1 suppressed the formation of ADM and PanINs (in other words, HSF1 inhibition may suppress pancreatic cancer initiation in KC mice)." (PMID 33422093, 2021). "However, vehicle KC mice had a number low-grade PanINs which indicated the initiation of pancreatic cancer; nevertheless, after treatment with KRIBB11, the AB/PAS+ blue area was obviously reduced, which demonstrates that HSF1 inhibition may suppress the formation of PanINs." (PMID 33422093, 2021). "However, the role of HSF1 in the tumorigenesis of human pancreatic cancer is not yet clear." (PMID 28482903, 2017).
prostate carcinoma (24 papers, 2010 to 2025). A carcinoma that arises from epithelial cells of the prostate gland. "For prostate cancer-specific death, a univariate Cox proportional hazards model showed that strong nuclear HSF1 staining raised the risk with a HR of 2.62 (95% CI 1.21–5.67; p = 0.015)." (PMID 30131848, 2018). "Statistically significantly elevated HSF1 levels were found to be associated with high grade group prostate cancer, positive lymph node status and metastasis, all signs of progressing disease." (PMID 30131848, 2018). "It has been more than a decade since HSF1 was observed to have an association with colorectal and prostate cancers." (PMID 29088759, 2017). "We hypothesized that the expression status of HSF1 may be associated with progression and aggressiveness of prostate cancer and that HSF1 can be utilized for outcome prognostications of patients who have undergone radical prostatectomy." (PMID 30131848, 2018). "In this study a clinical significance of HSF1 in prostate cancer is demonstrated: increased HSF1 expression associates with disease progression and independently predicts initiation of secondary therapy and poor disease-specific survival of prostate cancer patients after radical prostatectomy." (PMID 30131848, 2018). "In order to assess the utility of HSF1 as a prognostic marker further a competing risk analysis was performed where the probability to die specifically from prostate cancer, to die from other reasons, or to stay alive were compared in relation to the expression status of nuclear HSF1." (PMID 30131848, 2018). "In humans, HSF1 and its associated heat shock proteins are upregulated in the majority of tumor tissue types (e.g. lymphoma, lung, breast and prostate cancer), and are involved in regulating tumor cell hyperproliferation, metabolism, metastasis and chemotherapy resistance." (PMID 25199534, 2014). "Heat shock factor 1 (HSF1) is associated with tissue-specific tumorigenesis in a number of mouse models, and has been used a as prognostic marker of cancer types, including breast and prostatic cancer." (PMID 25199534, 2014). "To address this, and the fact that multiple HSPs and HSF1 have been implicated in AR signaling, we explored the clinical relevance of the GO cellular response to heat gene expression signature (which includes multiple HSPs and HSF1) in advanced prostate cancer." (PMID 39787247, 2025). "HSF1 is frequently overexpressed and activated in a wide range of cancers, including prostate cancer, and hijacked by cancer cells to promote their survival in harsh tumor microenvironments and during metastasis." (PMID 41028522, 2025). "A notable direct inhibitor of HSF1, DTHIB (Direct Targeted HSF1 InhiBitor), achieves its effect by accelerating nuclear HSF1 degradation and has shown strong efficacy in multiple models of resistant prostate cancer." (PMID 40287736, 2025). "Taken together, these data, alongside other studies that have interrogated HSF1 pathway inhibition in prostate cancer models, support the biological and clinical relevance of HSPs in mCRPC." (PMID 39787247, 2025). "We further describe preclinical therapeutic and mechanistic studies to support the potential for the clinical-stage developmental HSF1 pathway inhibitor in prostate cancer." (PMID 39787247, 2025). "DTHIB binds HSF1 directly and degrades HSF1 in the nucleus, thereby decreasing its nuclear activity and ultimately lowering its transcriptional activity in prostate cancer." (PMID 39850800, 2024). "Along with that, increased HSF1 expression has been found in a wide range of human cancers, including cervix, colon, breast, lung, liver, pancreatic, and prostate carcinomas." (PMID 39850800, 2024). "A recent study discovered that HSF1 enhances prostate cancer cell resistance to ferroptosis by modulating HSPE1, and that HSF1 knockdown can promote prostate cancer cell sensitivity to RSL3 therapy." (PMID 37868994, 2023).
prostate carcinoma (continued). "Given that bioinformatics analysis has shown that HSPE1 is mainly involved in the function of the ETC in mitochondria, HSF1/HSPE1 potentially represent crucial molecules affecting ROS levels in prostate cancer." (PMID 37351671, 2023). "In prostate cancer, HSF1 is reported as a robust predictive biomarker with high HSF1 mRNA expression and increased nuclear HSF1 shown in patients with advanced prostate cancer." (PMID 37958341, 2023). "Prostate cancer development and progression depend on androgen receptor (AR) signaling, and the HSF1-activated multichaperone complex (HSP90, HSP70, and HSP40) plays a crucial role in maintaining AR stability." (PMID 37351671, 2023). "Our investigation yielded novel findings, as we observed that the depletion of HSF1 in prostate cancer cell lines resulted in a decrease in HSPE1 expression and heightened susceptibility to ferroptosis triggered by the RSL3." (PMID 37351671, 2023). "The binding of HSF1 to the HSP90AA1 gene promoter region was increased in response to HSS in PC-3 prostate cancer cells." (PMID 36982267, 2023). "TCGA database was further used to verify the mRNA expression levels of HSF1 in prostate cancer using the UALCAN platform." (PMID 37351671, 2023). "Prostate cancer progression requires AR, which highly depends on HSF1-activated multichaperone complexes such as HSP70 and HSP40." (PMID 37958341, 2023). "The studies using prostate carcinoma cells and sections suggested that HSF1 can positively and negatively regulate cell cycle progression." (PMID 35053319, 2022). "SISU-102 robustly inhibits the HSF1 cancer gene signature and drives prostate cancer tumor regression in multiple mouse models." (PMID 36245043, 2022). "Since a higher expression level of HSF1 in prostate cancer cells and tissue sections from prostate cancer patients was reported, the roles of HSF1 in cancer cells have been examined by many research groups." (PMID 35053319, 2022). "Recently, a comprehensive study by Björk and colleagues proposed that HSF1 is a strong predictive biomarker in prostate cancer." (PMID 32408596, 2020). "One of the first studies describing the function of HSF1 in cancer showed that HSF1 contributes to the development of polyploidy in prostate carcinoma." (PMID 32408596, 2020). "Previously, we have noted elevated levels of HSF1 mRNA when comparing human luminal prostate cancer cell lines to basal, benign prostate epithelial cell lines." (PMID 30131848, 2018). "Our results on differential expression of HSF1 open up for therapeutic interventions also in prostate cancer." (PMID 30131848, 2018). "We pursued the clinical relevance of differential expression of HSF1 by immunohistochemistry (IHC) on a large primary prostate cancer cohort of radical prostatectomy samples, collected into TMA I." (PMID 30131848, 2018). "In conclusion, this study enhances the understanding of prostate cancer progression by demonstrating that the levels of HSF1 increases as the disease advances and that HSF1 status predicts disease-specific survival." (PMID 30131848, 2018). "Although we have demonstrated that HSF1 promotes invasion in prostate cancer cell lines and elevated expression has been detected in cancer cell lines and tumors, evidence for clinical significance of HSF1 in prostate cancer has not been demonstrated." (PMID 30131848, 2018). "The excessive amounts of both nuclear and cytoplasmic HSF1, independently of the metastatic site, highlight HSF1 as a key factor in invasion and metastasis of prostate cancer." (PMID 30131848, 2018). "All These data suggest a feed-forward regulation of HSF1 by CLU as we previously reported in prostate cancer." (PMID 25138053, 2014).
prostate carcinoma (continued). "In prostate carcinoma cells, a dominant negative construct of HSF1 dramatically alters the DNA content of PC3 cells and inhibits aneuploidy and Cyclin B1 stabilization." (PMID 24212658, 2011). "HSF1 expression has been shown to be elevated in prostate carcinoma compared to its normal counterpart." (PMID 24212658, 2011). "The potential role of HSF1 in cancer metastasis was first reported in prostate cancer where HSF1 overexpression was correlated with aggressiveness of the tumors." (PMID 24212658, 2011). "In prostate cancer cells, HSF1 also influences the development of an aneuploid state and mitotic progression." (PMID 24212658, 2011). "We therefore used a prostate cancer cell line, DU-145 in which we were able to induce profound reduction in HSF1 levels by knockdown with shRNA and yet maintain viability." (PMID 21085490, 2010). "In addition, NXP800 reduced both basal, and HSP90 inhibitor-induced, HSP72 protein expression levels, in contrast to its inactive chemical control CCT365248, confirming its important effect in blocking HSF1-activated HSP expression in prostate cancer cells." (PMID 39787247, 2025). "The HSF1-driven transcriptional program and its genome occupancy in mCRPC cells were distinct from those of castration-resistant prostate cancer cells and massively reprogrammed during the metastatic progression of castration-resistant prostate cancer cells." (PMID 41028522, 2025). "Therefore, although inhibition of the HSF1 pathway has been investigated in advanced prostate cancer models with promising antitumor activity, clinical translation remains challenging." (PMID 39787247, 2025). "Compared to benign controls, primary prostate cancer had higher levels of HSF1 mRNA (TCGA-PRAD)." (PMID 38172561, 2024). "Thus, HSF1 is potentially mainly involved in the proliferation and anti-apoptosis processes of prostate cancer." (PMID 37351671, 2023). "We next examined whether the gene expression of SCAN-TFs (MZF1, SCAND1, and SCAND2(P)) was correlated with HSF1 or HSF4 gene expression in prostate cancer specimens derived from patients." (PMID 36982267, 2023). "HSF1 inhibition has been proven to reduce cell proliferation in the treatment of prostate cancer." (PMID 37958341, 2023). "In a comparison between the non-metastatic human prostate carcinoma cell line PC-3 and the metastatic variant PC-3M, higher expression of HSF1 was found in both mRNA and protein." (PMID 35053319, 2022). "In addition, expression of a dominant-negative HSF1 construct reduced the aneuploid population in a prostate cancer cell line." (PMID 34922589, 2021). "In that study, a clinical prostate cancer dataset displayed high HSF1 mRNA expression, and the immunohistochemically analysis of tissue micro-arrays showed a dramatic increase in nuclear HSF1 in samples derived from patients suffering from advanced prostate cancer." (PMID 32408596, 2020). "Interestingly, in approximately 20% of the prostate cancer samples with HSF1 expression status, HSF1 was also detected in the cytoplasm, where it was scored as negative (no staining) or positive." (PMID 30131848, 2018). "This study suggests that HSF1 is a driver of prostate cancer progression and could serve as an informative biomarker for stratifying patients after radical prostatectomy." (PMID 30131848, 2018). "Finally, to verify HSF1 stainings on TMAs and since HSF1 levels, both mRNA and protein, were found to increase with prostate cancer progression, we performed IHC on a large cohort from advanced prostate cancers (TMA II)." (PMID 30131848, 2018). "Next, we studied the relationship between HSF1 expression and prostate cancer survival." (PMID 30131848, 2018). "Since HSF1 has been demonstrated to be a strong promoter of oncogenesis, we hypothesized that HSF1 would hold clinical significance in prostate cancer." (PMID 30131848, 2018).
prostate carcinoma (continued). "Likewise, in the chorioallantoic membrane in vivo model, tumors derived from prostate cancer cell lines showed reduced growth upon knock-down of HSF1 expression." (PMID 30131848, 2018). "Here, we identified HSF1 as a potential biomarker in mRNA expression datasets on prostate cancer." (PMID 30131848, 2018). "It was reported that HSF1 is upregulated in prostate cancer and HCC." (PMID 25199534, 2014). "This suggests that HSF1 could serve as a novel prognostic marker in prostate cancer." (PMID 30131848, 2018). "The clinical relevance of HSF1 in prostate cancer is, however, unknown." (PMID 30131848, 2018). "Next, we analyzed the impact of targeting the heat shock factor 1 (HSF1) pathway, with an inhibitor in clinical development, namely, NXP800 (formerly CCT361814), in models of treatment-resistant prostate cancer." (PMID 39787247, 2025). "We demonstrate the effects of targeting the HSF1 pathway, central to cellular stress, with an inhibitor in clinical development, namely, NXP800, in prostate cancer." (PMID 39787247, 2025). "After screening the downstream proteins of HSF1, we found that HSPE1 exhibited the strongest correlation with HSF1 in prostate cancer, and HSPE1 mainly functions in maintaining the mitochondrial ETC." (PMID 37351671, 2023). "Targeting the HSF1 pathway with the inhibitor NXP800 decreases HSP72 expression, activates the unfolded protein response, and inhibits AR- and E2F-mediated activity, inhibiting the growth of treatment-resistant prostate cancer models." (PMID 39787247, 2025). "Wu and colleagues observed elevated HSF1 mRNA and protein levels in metastatic prostate cancer cell lines (PC3M) compared to non-metastatic lines (PC3)." (PMID 40287736, 2025). "In conclusion, HSF1 may alleviate ROS and MDA levels to enhance the resistance of prostate cancer cells to ferroptosis by regulating HSPE1." (PMID 37351671, 2023). "In summary, the upregulation of HSF1 and HSPE1 may have significant implications in the development of prostate cancer, particularly in relation to cellular proliferation and defense against oxidative stress." (PMID 37351671, 2023). "In addition, HSF1 alleviates ROS and MDA levels to enhance the resistance of prostate cancer cells to ferroptosis by regulating HSPE1 in vitro, and HSF1 knockout promotes the susceptibility of PC to RSL3 treatment by increasing ferroptosis in vivo." (PMID 37351671, 2023). "In contrast to HSF1, HSF2 appears to function as a tumor suppressor in prostate cancer." (PMID 32408596, 2020). "We recently demonstrated that the absence of HSF1 renders prostate cancer cell lines in a non-differentiating acinar state, non-invasive, and prone to cell death in 3D organotypic cell culture." (PMID 30131848, 2018). "Intriguingly, a clear majority (83%) of the prostate cancer cores showed intermediate to strong HSF1 expression, while 70% of the benign cores showed negative or weak HSF1 expression." (PMID 30131848, 2018). "Moreover, simultaneous inhibition of HSF1 and CBS significantly enhances the suppression of prostate cancer cell proliferation and reduces transsulfuration pathway metabolites, underscoring a potent strategy for tackling prostate cancer progression." (PMID 39062461, 2024). "Overexpression of HSF1 enhanced the development of polyploidy, whereas reduction in HSF1 activity partially restored diploid DNA content in PC-3 cells, a human prostate cancer cell line that neither expresses the androgen receptor nor the prostate-specific antigen." (PMID 32408596, 2020).